CCNC (cyclin C)
Description:
Component of the Mediator complex, a coactivator involved in regulated gene transcription of nearly all RNA polymerase II-dependent genes. Mediator functions as a bridge to convey information from gene-specific regulatory proteins to the basal RNA polymerase II transcription machinery. Mediator is recruited to promoters by direct interactions with regulatory proteins and serves as a scaffold for the assembly of a functional preinitiation complex with RNA polymerase II and the general transcription factors. Binds to and activates cyclin-dependent kinases CDK8 and CDK19 that phosphorylate the CTD (C-terminal domain) of the large subunit of RNA polymerase II (RNAp II), which may inhibit the formation of a transcription initiation complex.
Synonyms: hSRB11; CycC; SRB11
Tractability: Small molecule: a structure with a bound ligand is known; a high-quality ligand is known. PROTAC: ubiquitination databases record sites on it.
Target class: Other cytosolic protein
Gene: Protein-coding gene on chromosome 6 (99,542,387 to 99,568,825, reverse strand). Ensembl gene ENSG00000112237.
Subcellular location: Nucleus
Subcellular location (Human Protein Atlas): Nucleoplasm; Cytosol
Pathways (Reactome):
Disease: Constitutive Signaling by NOTCH1 HD+PEST Domain Mutants; Constitutive Signaling by NOTCH1 PEST Domain Mutants; RSV-host interactions
Gene expression (Transcription): Generic Transcription Pathway; MLL4 and MLL3 complexes regulate expression of PPARG target genes in adipogenesis and hepatic steatosis
Signal Transduction: NOTCH1 Intracellular Domain Regulates Transcription; SMAD2/SMAD3:SMAD4 heterotrimer regulates transcription
Developmental Biology: Transcriptional regulation of white adipocyte differentiation
Metabolism: PPARA activates gene expression
Gene Ontology:
Molecular function: cyclin-dependent protein serine/threonine kinase regulator activity; identical protein binding; protein binding
Biological process: G0 to G1 transition; negative regulation of Notch signaling pathway; positive regulation of transcription by RNA polymerase II; regulation of transcription by RNA polymerase II
Cellular component: CKM complex; cyclin-dependent protein kinase holoenzyme complex; mediator complex; nucleoplasm; nucleus
Genetic constraint (gnomAD): Loss-of-function variants: 2 observed, 8.54 expected, observed/expected ratio (o/e) 0.23, 90% interval 0.095 to 0.74. That is too few expected variants to judge how well the gene tolerates losing a copy. Missense variants: 23 observed, 51.44 expected, observed/expected ratio (o/e) 0.45, 90% interval 0.32 to 0.63. Synonymous variants: 17 observed, 16.35 expected, observed/expected ratio (o/e) 1.04, 90% interval 0.71 to 1.55.
Homologues: Orthologues: chimpanzee CCNC (100% identical), dog CCNC (99% identical), rabbit CCNC (99% identical), mouse Ccnc (99% identical), guinea pig CCNC (99% identical), pig CCNC (97% identical), tropical clawed frog ccnc (95% identical), macaque CCNC (94% identical), zebrafish ccnc (94% identical), rat Ccnc (89% identical).
Diseases named in the same sentence as CCNC in open-access papers:
CCNC is named in the same sentence as 39 diseases in open-access papers, as found by Europe PMC text mining. Sharing a sentence is not in itself a finding about the gene and the disease. The quoted sentences say what the papers report.
acute lymphoblastic leukemia (6 papers, 2015 to 2025). Leukemia with an acute onset, characterized by the presence of lymphoblasts in the bone marrow and the peripheral blood. "It has been reported that CCNC is deleted in patients with acute lymphoblastic leukemia, supporting the possibility that the CCNC gene is closely linked to tumor suppressor genes." (PMID 34071419, 2021). "Because the cyclin C (CCNC) gene is often deleted in malignancies such as acute lymphoblastic leukemia and osteosarcoma, CCNC and CDK19 may function as tumor suppressors." (PMID 28885545, 2017). "Mechanistic details have started to emerge on how cyclin C acts as a tumor suppressor in T-cell acute lymphoblastic leukemia (T-ALL) Here, aberrant NOTCH1 expression is a causative factor in T-ALL development." (PMID 40358161, 2025). "A further layer of complexity was recently added by the finding that the CDK8/cyclin C axis acts in a tumor-suppressive manner in T-cell acute lymphoblastic leukemia (T-ALL)." (PMID 31248103, 2019).
gastric cancer (6 papers, 2020 to 2025). A primary or metastatic malignant neoplasm involving the stomach. "HACE1‐mediated ubiquitylation of cyclin C sheds light on a better understanding of cisplatin‐associated resistance in gastric cancer patients." (PMID 35343092, 2022). "Disruption of HACE1 and cyclin C interaction by CCNC deletion or site mutation mitigated the mitochondrial ROS production as well as the cisplatin‐induced apoptosis in gastric cancer cells." (PMID 35343092, 2022). "Mutation on the ubiquitylation sites of cyclin C inhibits cisplatin‐induced cell death, shedding light on a better understanding of cisplatin‐associated resistance in gastric cancer patients." (PMID 35343092, 2022). "Therefore, cisplatin-mediated degradation of Cyclin C is the mechanism of apoptosis in gastric cancer which can be impaired upon mutations in ubiquitinating sites of Cyclin C." (PMID 36769170, 2023). "Ubiquitylation of cyclin C by HACE1 regulates cisplatin‐associated sensitivity in gastric cancer." (PMID 35343092, 2022). "HACE1 mediates the non-proteolytic ubiquitination of cyclin C in the cytoplasm, thereby promoting nuclear–mitochondrial translocation of cyclin C and maintaining the chemosensitivity of gastric cancer cells to cisplatin." (PMID 40948788, 2025). "Cyclin C is another type of Cyclin that has been studied in the context of drug resistance in gastric cancer." (PMID 36769170, 2023). "HACE1 adds ubiquitin to Cyclin C for its degradation in gastric cancer cells when treated with cisplatin." (PMID 36769170, 2023). "The depletion of cyclin C in the gastric cancer HGC27 cell line resulted in high cell viability and mitochondrial respiration levels, as well as minimal apoptosis and mitochondria‐derived reactive oxygen species (ROS) levels in the face of cisplatin treatment." (PMID 35475325, 2022). "While in human gastric cancer cell lines, we found that loss of HACE1 reduced oxidative stress and promoted cisplatin resistance by preventing cyclin C‐induced mitochondrial dysfunction and ROS synthesis." (PMID 35343092, 2022). "A cDNA microarray‐based study found that cyclin C was lowly expressed in tumour tissues compared with normal ones in gastric cancer." (PMID 35475325, 2022). "Recently, Jiang and colleagues revealed a novel mechanism of HECT domain and ankyrin repeat‐containing E3 ubiquitin‐4 protein ligase 1 (HACE1) ubiquitylation modifying cyclin C to regulate tumour cell resistance to cisplatin in gastric cancer." (PMID 35475325, 2022). "In the present study, we elucidated a novel mechanism by which disorganisation of HACE1–cyclin C interaction drives gastric cancer cell resistance to cisplatin treatment by deregulating mitochondrial‐associated oxidative stress." (PMID 35343092, 2022). "This study aimed to investigate the role of cyclin C and its ubiquitylation in regulating cisplatin resistance in gastric cancer." (PMID 35343092, 2022). "So far, little is known about the role of cyclin C in regulating mitochondrial dynamics in response to cisplatin stimulation in gastric cancer." (PMID 35343092, 2022). "Our data show that CCNC is downregulated in gastric cancer and that the treatment with rhIL-33 further reduces its expression." (PMID 34071419, 2021). "CCNC is among the genes with reduced copy numbers and mRNA expression in gastric cancer vs. normal tissue." (PMID 34071419, 2021). "Therefore, Cyclin G2 and Cyclin L2, along with Cyclin C, are involved in negatively influencing the growth of gastric cancer cells." (PMID 36769170, 2023). "Cyclin C regulates cisplatin sensitivity in gastric cancer cells." (PMID 36769170, 2023). "Thus, HACE1‐mediated ubiquitylation modification of cyclin C plays a role in regulating cell response to cisplatin treatment in gastric cancer." (PMID 35343092, 2022). "We next investigated whether ubiquitylation of cyclin C is essential for increasing drug sensitivity to cisplatin in gastric cancer cells via affecting mitochondrial stability." (PMID 35343092, 2022).
gastric cancer (continued). "In the present study, cisplatin‐induced cyclin C translocation was also observed in MGC803, MKN28 and HGC27 cells, three human gastric cancer cell lines, indicating that the nuclear–mitochondrial translocation of cyclin C is a general phenomenon in cisplatin stimulation." (PMID 35343092, 2022). "However, the role of cyclin C ubiquitylation in mitochondrial dysfunction in gastric cancer cells challenged with cisplatin remains unclear." (PMID 35475325, 2022). "In this study, we identified that in gastric cancer, HACE1 catalyses the ubiquitylation modification of cyclin C when it translocates to cytoplasm under the stimulation by cisplatin treatment." (PMID 35343092, 2022). "The immunofluorescence staining revealed that fluorescent signals of cyclin C and HACE1 were colocalised in the cytoplasm of cultured HGC27 challenged with cisplatin (10 μM) and in the samples from two gastric cancer patients who received neoadjuvant therapy." (PMID 35343092, 2022). "Indeed, cyclin C was found in mitochondria in MGC‐803, MKN28 and HGC27 gastric cancer cells stimulated with cisplatin." (PMID 35343092, 2022).
breast carcinoma (4 papers, 2017 to 2023). "In the same study, we found that higher expression of CDK8, CDK19 and Cyclin C is associated with shorter relapse-free survival in human breast cancers." (PMID 28147342, 2017). "CDK8 in complex with cyclin C is a transcriptional regulator that mediates several carcinogenic pathways in breast cancer." (PMID 37175852, 2023). "In contrast, CDK8, CDK19, and CCNC showed similar amplification frequencies in breast cancers and sarcomas." (PMID 31382571, 2019). "The other cancers with a substantial frequency of CDK8/CDK19/CCNC gene amplification were breast cancers and sarcomas." (PMID 31382571, 2019). "Gene amplification of CCNC is also the most frequent type of genetic alterations in breast cancers." (PMID 30906311, 2019). "In particular, co-amplification of CDK8 with CCNC and/or CDK19 was found in some cases of prostate and breast cancer." (PMID 31382571, 2019). "Expression of CDK8, its paralog CDK19 and their binding partner Cyclin C are negative prognostic markers in breast cancer." (PMID 28147342, 2017).
osteosarcoma (4 papers, 2017 to 2019). A usually aggressive malignant bone-forming mesenchymal neoplasm, predominantly affecting adolescents and young adults. "Heterozygous deletion of cyclin C gene (CCNC) has been linked to the progression of acute lymphoblastic leukemia, osteosarcoma, and thyroid cancer, suggesting that cyclin C is a bona fide tumor suppressor." (PMID 29337889, 2018). "A subset of osteosarcomas contain deletions in the 6q16-6q23 chromosomal region, which contains both CCNC and CDK19." (PMID 28416637, 2017). "Although cyclin C mitochondrial relocalization and mitochondrial fragmentation was observed in HeLa cells, the human osteosarcoma U2O2 cells displayed nuclear cyclin C release and mitochondrial localization in the absence of oxidative stress but did not induce fragmentation." (PMID 30621145, 2019).
melanoma (3 papers, 2014 to 2021). A malignant, usually aggressive tumor composed of atypical, neoplastic melanocytes. "The Mediator kinase CDK8 and its paralog CDK19, together with their binding partner Cyclin C (CCNC), have been implicated through experimental studies in several malignancies, including cancers of the colon, breast, prostate, pancreas, melanoma, and leukemias." (PMID 31382571, 2019). "CCNC expression was also relatively uniform, but CCNC RNA was apparently lower in melanomas." (PMID 31382571, 2019). "A recent study of miR-206 in melanoma showed that it targeted CDK4, Cyclin C and Cyclin D1 which were cell cycle genes." (PMID 25255814, 2014). "Moreover, in vitro studies have shown that several genes are linked to melanomagenesis in the co-deleted region, including ARID1B, CCNC, and ROS1, although none have yet been shown to be functionally important in melanoma in vivo." (PMID 34140478, 2021).
cancers of the colon (2 papers, 2019 to 2022). "In addition, the expression of cyclin-related proteins (Cyclin C, Cyclin D1, Cyclin E1) in colon cancer cell HT29 in each group was determined by western blot." (PMID 35615948, 2022). "Among the GI tract cancers, CDK8 was amplified much more frequently than CDK19 or CCNC, with no amplification of CDK19 or CCNC found in colon cancers (not shown)." (PMID 31382571, 2019).
leukemia (2 papers, 2015 to 2019). A malignant (clonal) hematologic disorder, involving hematopoietic stem cells and characterized by the presence of primitive or atypical myeloid or lymphoid cells in the bone marrow and the blood. "In human, CCNC and CDK19 genes lie very close to each other on the 6q21 region of the human chromosome 6, a region that is frequently deleted in multiple malignancies including breast, lung, ovarian, prostate carcinomas, leukemia and osteosarcoma." (PMID 25914884, 2015).
Obesity (2 papers, 2015 to 2023). Accumulation of substantial excess body fat. "Recently, remarkably decreased protein amounts of cyclin-dependent kinase 8 (CDK8) and Cyclin C (CycC) were detected in obesity in comparison with normal livers." (PMID 36769165, 2023).
T-cell acute lymphoblastic leukaemia (2 papers, 2015 to 2018). "Consequently, CCNC ablation but also Cyclin C heterozygosity resulted in elevated ICN1 levels and accelerated T-cell acute lymphoblastic leukaemia (T-ALL) identifying CCNC as a haplosufficient tumor suppressor." (PMID 30693281, 2018).
Promyelocytic Leukemia (1 paper, 2024). "In the G2M Checkpoint hallmark, genes such as B-Cell Lymphoma 3 (BCL3), Cyclin C (CCNC), and Promyelocytic Leukemia (PML) are downregulated under Fe ion irradiation conditions compared to photon irradiation conditions." (PMID 39286254, 2024).
Sepsis (1 paper, 2024). Sepsis is defined as life-threatening organ dysfunction caused by a dysregulated host response to infection. "To determine the contribution of the Ccn sRNAs to S. pneumoniae virulence, we initially made single deletions of ccnA, ccnB, ccnC, ccnD, or ccnE and a quintuple deletion of all five ccn genes in the archetypal serotype 2 S. pneumoniae strain D39, which causes rapid killing of mice by sepsis." (PMID 39361718, 2024).
uterine cancer (1 paper, 2019). Primary or metastatic malignant neoplasm involving the uterine corpus and/or the cervix. "On the other hand, uterine cancers were unique in showing a high frequency of point mutations in CDK8/CDK19/CCNC." (PMID 31382571, 2019). "The impact of the CDK8/CDK19/CCNC mutations found in uterine cancers is unknown, but we note that uterine cancers were also one of the types that showed correlations between the expression of CDK8 and CDK19 and shorter survival." (PMID 31382571, 2019). "Among other cancer types with relatively frequent alterations of CDK8, CDK19, or CCNC, we note cancers of the uterus, where mutations of these genes were found more frequently than in the other cancer types; most of these were missense mutations of unknown significance." (PMID 31382571, 2019).
cancer (26 papers, 2013 to 2026). A tumor composed of atypical neoplastic, often pleomorphic cells that invade other tissues. "In this way, CDK8/cyclin C can keep cancer cells alive by promoting replication stress response of cancer cells and thus reducing DNA damage." (PMID 38606172, 2024). "Excepting the dominant-negative regulator of STAT3α, STAT3β can repress the expression of Bcl-xL, p21, cyclin D1, and cyclin C, inducing apoptosis and cell cycle arrest in cancer cells." (PMID 33670049, 2021). "Although CCNC loss of function mutations have been reported in some patients with T-ALL 23, the involvement of membrane-bound DLL4 in cancer cells remained elusive until our present proof of concept study showing DLL4 involvement in the human disease." (PMID 33408769, 2021). "As shown by GSCA, except CCNY, CCNT2, and CCNC, all cyclin genes were differentially expressed in different cancers, among which the number of genes in COAD was the highest, with 16 genes differentially expressed in total." (PMID 33996604, 2021). "Cyclin C was proved to suppressed cancer, it is also a downstream target of emodin found by this study." (PMID 33407495, 2021). "Dysregulation of CDK8 (Cyclin-Dependent Kinase 8) and its regulatory partner CycC (Cyclin C), two subunits of the conserved Mediator (MED) complex, have been linked to diverse human diseases such as cancer." (PMID 32463833, 2020). "The duality of cyclin C function is perhaps best illustrated by its suppressing and enhancing role in cancer development." (PMID 30621145, 2019). "Analysis of CDK8/CDK19/CCNC alterations identified several cancer subtypes where these genes were frequently altered." (PMID 31382571, 2019). "In the following paragraphs, we summarize the current knowledge on cyclin C biology including its dual role in eliciting stress signaling while highlighting potential implications relevant to cancer and cancer therapy." (PMID 30621145, 2019). "Nevertheless, due to its utility, the cyclin C-mitochondrial axis is emerging as a prospective therapeutic target for both cancer and neurodegenerative diseases." (PMID 29337889, 2018). "PTGS2 was the only marker out of the 24 analyzed that was more frequently methylated in CCNC than in cancer cores." (PMID 25548652, 2014). "However, little is known about the role of cyclin C in mitochondrial dysfunction in cancer cells challenged with cisplatin." (PMID 35475325, 2022). "Although these findings may have important implications for cancer research as well as clinical applications, the exact molecular mechanism of cyclin C-dependent activation of the apoptotic machinery deserves future investigation." (PMID 30621145, 2019). "Since evasion of apoptosis is one of the hallmarks of cancer, the direct role of cyclin C at the mitochondria could straightforwardly explain its observed tumor suppressive activity." (PMID 30621145, 2019). "In some cases, the CCNC core was more methylated than the cancer core." (PMID 25548652, 2014). "The differential methylation of CCNC and cancer cores may identify critical genes and pathways that are required for the development of histologically visible cancer." (PMID 25548652, 2014). "Cell cycle role of CCNC and its effect on several cancer types were reported by several authors." (PMID 24088394, 2013). "Therefore, a pharmacological method to disrupt cyclin C-Med13 interaction may allow sensitization of cancer cells to chemotherapy." (PMID 30621145, 2019). "Owing to the essential role that cyclin C plays in stress signaling, future investigations into the direct function of cyclin C at the mitochondria may translate into new discoveries that would prove critical in combating both cancer and degenerative diseases." (PMID 30621145, 2019).